CD4 (CD4 molecule)
Diseases named in the same sentence as CD4 in open-access papers (continued):
Sharing a sentence is not in itself a finding about the gene and the disease.
mycosis fungoides (continued). "Mycosis fungoides (MF) and Sézary syndrome (SS) are the most prevalent forms of cutaneous T-cell lymphoma (CTCL) and are characterized by the proliferation of CD4+ T-helper cells." (PMID 40427608, 2025). "Immunohistochemistry revealed CD4+, CD7-, and CD20 cells, consistent with mycosis fungoides, leading to the initiation of oral methotrexate, but without clinical improvement." (PMID 40918840, 2025). "Mycosis fungoides (MF) is the most common of the CTCL subtypes, encompassing 65% of all CTCLs, the vast majority of which are CD4+, with an estimated less than 5% of cases of MF showing a CD8+ phenotype." (PMID 39272944, 2024). "Mycosis fungoides (MF) is the most common subtype of cutaneous T cell lymphoma (CTCL) and is characterized by the clonal expansion of transformed skin-resident memory CD4+ T cells." (PMID 37669110, 2023). "Mycosis fungoides (MF) is the most common form of cutaneous T-cell lymphoma (CTCL) and is characterized by epidermotrophism of malignant CD4+ T-lymphocytes." (PMID 37175780, 2023). "Considering the grave effects caused by SOCS1 absence and more particularly one-copy deletion of SOCS1 in CD4+ T cells in MF, the present long-term in vivo experiments focused on the impact of conditional Socs1 knockout in CD4+ T cells to mimic early-stage mycosis fungoides." (PMID 37664523, 2023). "Mycosis fungoides (MF) is a type of cutaneous T-cell lymphoma (CTCL) that originates from epidermal T cells, and it expresses the T-cell receptor (TCR) and CD4+ immune cell markers." (PMID 35154913, 2022). "Mycosis fungoides (MF) is the most common type of CTCL and originates from mature, skin-tropic CD4+ T helper cells." (PMID 36428999, 2022). "In both mycosis fungoides and Sezary syndrome, clonal T lymphocytes commonly exhibit a CD4+ CD3+ phenotype in the absence of CD7 and CD26 expression." (PMID 38254826, 2024). "While impaired activation of CD4 + and CD8 + T cells is not considered the direct cause of mycosis fungoides, for which the exact cause is not fully understood, it is believed to play a role in the pathogenesis of the disease." (PMID 38280109, 2024). "Mycosis fungoides (MF), the most common type of Cutaneous T cell Lymphoma (CTCL), is characterized by an inflamed skin intermixed with proliferating malignant mature skin-homing CD4+ T cells." (PMID 36505769, 2022). "The immunophenotypic profile revealed positivity for CD2, CD4, CD7 associated with negative markers CD3, CD5, CD8, CD20, supporting the diagnosis of mycosis fungoides." (PMID 35573524, 2022). "Studies conducted by flow cytometry tests on CD4+ T cells population identified a specific phenotype (CD26− or CD7− T cells with bright or dim CD3 or CD4 or bright CD7) that represents the phenotype for diagnosis of Sézary syndrome (SS) and mycosis fungoides and correlates with disease progression." (PMID 35205639, 2022). "Mycosis fungoides (MF) is the most frequent T-cell lymphoma of the skin and seems pathogenetically related to a monoclonal T-cell receptor (TCR) gene rearrangement, leading to a monoclonal proliferation of cutaneous CD4-positive T lymphocytes." (PMID 33763381, 2021). "Due to the nonspecific nature of these lesions, CD4-positive cutaneous T-cell lymphoma (CTCL) is often misdiagnosed as either mycosis fungoides or Sezary syndrome." (PMID 32847118, 2020). "Due to the nonspecific nature of these lesions, CD4-positive CTCL is often misdiagnosed as either Mycosis Fungoides or Sezary Syndrome." (PMID 26380134, 2015). "Mycosis fungoides (MF) and Sézary syndrome (SS), the most common types of cutaneous T-cell lymphoma (CTCL), are characterized by proliferation of mature CD4+ T-helper cells." (PMID 34830466, 2021). "Mycosis fungoides (MF) and other primary CTCL frequently derive from the CD4+ T-helper subsets." (PMID 37500795, 2023).
mycosis fungoides (continued). "Cutaneous T cell lymphoma (CTCL), including the most common subtypes mycosis fungoides (MF) and Sézary syndrome (SS), represents a group of non-Hodgkin lymphomas of skin-homing, usually CD4+, malignant T cells." (PMID 30018745, 2018). "Some authors also regard the CD4:CD8 ratio as a nonspecific finding, given the existence of cases of mycosis fungoides with predominant CD8." (PMID 15543371, 2004).
candidiasis (70 papers, 2006 to 2025). Infection with the organism Candida. "The CD4+ T-lymphocyte count emerged as the most significant predictor, with a coefficient of −0.30 (p < 0.001), indicating a 26% reduction in candidiasis risk per 100-cell/μL increase (OR = 0.74)." (PMID 40428813, 2025). "Studies of SLE patients have also shown that certain pharmacological treatments such as cytotoxic agents and CD4+ count are associated with candidiasis or infections." (PMID 36000133, 2022). "The location and intensity of candidosis in HIV patients are closely associated with a low CD4 count trend." (PMID 34356934, 2021). "The low absolute CD4+T-lymphocyte count has traditionally been cited as the greatest risk factor for the development of Oral Candidiasis." (PMID 32774600, 2020). "In an adaptive immunity OPC rechallenge model using a derivate of the pathogenic C. albicans strain SC5314, CD4+ Th17 cells protect from mucosal Candida infection but can be compensated by other IL-17-producing cells in CD4-deficient hosts." (PMID 33193324, 2020). "In this pilot project, we describe the diagnostic potential of quantitating Candida-reactive, CD4/CD69/CD154 positive lymphocytes in blood of patients with invasive Candida infection." (PMID 29988394, 2018). "Some HIV-associated oral lesions such as candidiasis and hairy leukoplakia are more common as CD4 T cell counts decline and are reversed with immune reconstitution." (PMID 26930571, 2016). "T cells are pivotal immune cells during C. albicans infection and patients with decreased CD4+ T cells were found to be highly susceptible to mucocutaneous and invasive Candidiasis." (PMID 27790210, 2016). "A CD4 count <200 cells/μl was a significant risk factor for acquiring candidiasis among HAART-naive HIV patients." (PMID 23510937, 2013). "A CD4 count <200 cells/μl was a significant risk factor for acquiring candidiasis only among HAART-naive HIV patients (OR = 4.37, 95% CI = 1.60–11.95, p=0.0042)." (PMID 23510937, 2013). "Progressive cell-mediated immunodeficiency with decrease of CD4+ lymphocyte count to less than or equal to 200 cells/mm3 is a major risk factor for colonization with Candida species and development of candidiasis." (PMID 16423306, 2006). "Progressive cell-mediated immunodeficiency with decrease of CD4+ lymphocyte count to ≤ 200 cells/mm3 is a major risk factor for colonization with Candida species and development of candidiasis." (PMID 16423306, 2006). "HIV causes systemic CD4 + T-cell destruction, and results in impaired cell-mediated immunity, which leads to the inevitable emergence of various opportunistic infections, one example of which is the development of candidiasis." (PMID 36722096, 2023). "This is in line with other studies that showed low CD4 was associated with candidiasis." (PMID 36000133, 2022). "When the CD4 count is less than 400 cells/mm3, there is an increased risk of oral and vaginal candidosis; below 200 cells/mm3, there is risk of oropharyngeal candidosis; and when the CD4 count is less than 30 cells/mm3, there is an increased risk of esophageal candidosis or systemic candidemia." (PMID 34356934, 2021). "This study was conducted in HIV positive patients to find out the prevalence of Candidiasis and various Candida species implicated, and to study the relationship of Candida infections to immunological markers represented by CD4 T+ cells and Absolute Lymphocyte counts." (PMID 23205253, 2012). "Differences in immune status, diagnostic approaches, CD4 levels, availability of ART, treatment of candidiasis and geographic location have been outlined as possible reasons for differences in the prevalence of oropharyngeal and oral candidiasis." (PMID 39593167, 2024). "In oral and intestinal inflammation due to oral Candida infection, the Treg population has a multilayered protective role, one for IL-17A induction in CD4+ T cells and another for immunomodulation to prevent excessive inflammation." (PMID 36923589, 2023).
candidiasis (continued). "Another study in South Africa showed that oral Candidiasis was negatively correlated with CD4 count in patients on treatment; which proves that immunosuppression is a risk factor for the emergence of oral candidiasis." (PMID 37545607, 2023). "Severe symptoms indicative of candidiasis were seen in only two patients with CD4+ T-cell counts >300 cells/μl." (PMID 35250957, 2022). "Se encontró una relación estadísticamente significativa entre la candidiasis oral y un recuento de CD4 menor a 100 células/mm3 (p=0,008)." (PMID 35867921, 2022). "Asimismo, se encontró una relación estadísticamente significativa entre la candidiasis oral y un recuento de CD4 menor de 100 células/mm3 (p=0,008)." (PMID 35867921, 2022). "Oral candidosis responded favorably, and substantial relief was obtained with a concurrent increase in T cells and the CD4/CD8 ratio." (PMID 34356934, 2021). "All these appear to be strong evidence for the role of CD4 cells in protection against systemic candidosis as well as an important immunoregulatory role for neutrophils." (PMID 34356934, 2021). "Several reports documented the significant association between both an increased candidal salivary carriage and the presence of clinically detectable candidosis in a patient with reduced CD4 count." (PMID 34772385, 2021). "Prophylaxis with intermittent prescription of fluconazole three times weekly is recommended when a CD4 count less than 200 cells/mm3 develops because nystatin often invites a poor response and rapid relapse of oral candidosis in HIV patients." (PMID 34356934, 2021). "CD4 T-cells: Historically, CD4+ T-cell immune responses have been believed to be protective against Candida infection." (PMID 34696267, 2021). "During HIV infection period, the incidence of candidiasis is related to reduce the immunity level of these patients due to decreased CD4+ cells, which is dependent on the use of antiviral therapy." (PMID 32922676, 2020). "The importance of CD4+ cells in protection against oral candidosis is highlighted by higher disease incidence in individuals with reduced CD4+ cell numbers." (PMID 31718115, 2019). "Confirming our initial day 3 PI, intracellular flow, Nos3-/- mice showed significantly higher Th9 subset (CD4+IL-9+) and Th2 subset (CD4+IL-4+) induction due to dissemination candidiasis at days 2–6 PI." (PMID 31671151, 2019). "In this study, patients with CP and CD4+ T cells ≤200 cells/μL had a major prevalence of Candida infection (73.7%) than the one reported in previous studies." (PMID 31316513, 2019). "In the course of HIV infection, the rate of Candida infection is inversely related to the CD4+ T cells count." (PMID 31316513, 2019). "The percentage of CD4+ T cells in wild-type mice was significantly lower following Candida infection." (PMID 31668132, 2019). "In contrast, in immunodeficient transgenic mice with oral and gastrointestinal candidosis, the immune response was primarily mediated by CD4+ Th1 cells." (PMID 31718115, 2019). "Effects of p38γ/δ on inhibitory cell populations with deleterious roles during candidiasis, such as T‐regulatory cells, can also be considered since p38γ/p38δ deletion slightly decreased the recruitment of CD4+ cells in the kidney of infected mice." (PMID 29661910, 2018). "In the present study the mean CD4 T lymphocyte count in 88 patients with Candida infection was 142.6 cells/μL, with a range of 25–463 cells/μL and a standard deviation of ±72." (PMID 27092278, 2016). "In the delayed group, the incidence of candidiasis was significantly higher before therapy was started (13.59 versus 1.42; p-value <0.01), and occurred at a median CD4 T cell count of 259 cells/mm3 (IQR 222–309 cells/mm3)." (PMID 26930571, 2016). "One study in India revealed that candidiasis is a common lesion in patients with a mean CD4+ count of 212 /mm3, and hairy leukoplakia was presented in subjects with a mean CD4+ count of 97/ mm3." (PMID 25745611, 2015).
candidiasis (continued). "PPVs for oral manifestations to CD4+ less than 350 cells/mm3 were in a low range from 32.2% for melanotic hyperpigmentation to 48.2% for candidiasis." (PMID 25432363, 2014). "There is a significant relationship between antiretroviral therapy, CD4+ counts, and the prevalence of candidiasis." (PMID 23510937, 2013). "The improvement in CD4 cell counts of patients with candidiasis who were on ART was maximum in the regimen of the combination of Zidovudine, Lamivudine and Nevirapine." (PMID 23205253, 2012). "The CD4 cell counts of all the patients were estimated and correlated with the presence (or absence) of candidiasis." (PMID 23205253, 2012). "Two patients had candidemia (2.5%) and 1 had pulmonary candidiasis with candedemia, this patient had the lowest CD4 count (36 cells/mm3) and total lymphocyte count (582 cells /mm3) among all the patients with candidiasis." (PMID 23205253, 2012). "During the course of HIV infection, the rate of Candida infection is inversely related to the CD4 counts of the patient which in turn depends on the use of Anti-retroviral treatment." (PMID 23205253, 2012). "Some possible reasons are co-existence of other lesions or the effect of HAART, which can control candidiasis with an indirect effect on CD4+ count." (PMID 23346337, 2010). "It has long been believed that the CD4+T cell immune response protects against Candida infection." (PMID 38404288, 2024). "Thus, major aphthous ulcers, necrotizing ulcerative periodontitis, intraoral Kaposi's disease, oral leukoplakia, and candidiasis have been found to have a predictive value of finding CD4+ cell counts below 200/mm3 in HIV patients." (PMID 39114845, 2024). "The difference in prevalence across different countries and continents may be due to variations in oral hygiene, diagnostic approaches, CD4 levels, availability of HAART, treatment of candidiasis and geographic location." (PMID 38883750, 2024). "Se encontró, asimismo, una relación entre la candidiasis oral y recuentos de CD4 menores de 100 células/mm3, lo que se ha reportado en otros estudios y pone de presente el papel de la candidiasis oral como un marcador importante de debilitamiento del estado inmunológico de los pacientes con HIV." (PMID 35867921, 2022). "Th17 cells are differentiated from CD4+ helper T cells, which secrete IL-17, IL-22, and other cytokines and play an essential role in the host's resistance to Candida infection." (PMID 35783379, 2022). "The pathogens identified in this study mainly consisted of bacteria, candidiasis, CMV and herpes simplex virus, and age at the diagnosis, smoking, baseline SCr higher than 5.74 mg/dl, CD4+ T cell< 281 μl, and CYC therapy were independent risk factors for infection in patients with AAV." (PMID 29902982, 2018). "Antiretroviral protease inhibitors containing HIV aspartyl protease inhibitors could increase CD4 cell count and inhibited the fungal secretory aspartyl proteinases, thus leading to reduced Candida infection during mucosal invasion." (PMID 23356471, 2013). "Patients with candidiasis had CD4 counts less than 200 cells/mm3." (PMID 23205253, 2012). "Distribution of Various presentation of Candidiasis and CD4 counts in HIV positive patients." (PMID 23205253, 2012). "This difference in outcome could be related to a higher proportion of patients in the OPTIMA trial receiving anti-infective prophylaxis (87% for PCP and 53% for candidiasis with a CD4 count <200 per μl)." (PMID 21483491, 2011). "Bozza and colleagues reported that CD4+CD25+ regulatory T cells in candidiasis are strictly dependent on the expression of B7 costimulatory molecules by IL-10-producing DCs, and are involved in the IFNγ/IDO-dependent pathway that controls the local inflammatory pathology." (PMID 18221522, 2008).